ACE (angiotensin I converting enzyme)
Diseases named in the same sentence as ACE in open-access papers (continued):
Sharing a sentence is not in itself a finding about the gene and the disease.
Hypertension (continued). "Although in most surveys the prevalence of hypertension appears to be equal in women and men, sex-specific effects of ACE or AGT genes on hypertension have been reported recently." (PMID 15642127, 2005). "An additional 21 patients received ACE inhibitors after start of the current episode of AF because of either insufficiently treated hypertension or left ventricular dysfunction newly documented with echocardiography." (PMID 15667649, 2005). "The present study investigates the relationship between variants of the I/D ACE gene and M235T AGT gene, and the presence and severity of essential hypertension in a large homogeneous German population." (PMID 15642127, 2005). "The treatment of hypertension using diuretics or beta blockers was more cost-effective than the treatment using ACE inhibitors and calcium channel blockers." (PMID 12436155, 2002). "Treatment of hypertension with diuretics or beta blockers was more cost-effective than treatment with ACE inhibitors and calcium channel blockers." (PMID 12436155, 2002). "This work could facilitate the development of functional foods enriched with ACE-inhibitory peptides to help meet the growing demand for hypertension management." (PMID 41596878, 2026). "Enzymatic hydrolysis enables the production of protein hydrolysates enriched with bioactive peptides that possess antioxidant and angiotensin-converting enzyme (ACE) inhibitory activities, presenting promising potential for managing oxidative stress and hypertension." (PMID 41596852, 2026). "ZOFE, an ACE inhibitor, demonstrated significant anti-inflammatory activities by reducing inflammatory cytokines, thereby mitigating vascular inflammation, a key factor in hypertension and atherosclerosis." (PMID 41629568, 2026). "While ACE inhibitors are widely used for hypertension, their systemic effects on intestinal permeability and physical capacity in AD patients remain unclear." (PMID 41754844, 2026). "This classical understanding of the RAS has underpinned decades of therapeutic strategies targeting hypertension and cardiovascular disease, primarily through the use of angiotensin converting enzyme inhibitors (ACE-i), angiotensin receptor blockers (ARBs), and direct renin inhibitors." (PMID 41598680, 2026). "So, as a control drug for hypertension, we chose the ACE inhibitor most commonly used in practice." (PMID 40699692, 2025). "Consequently, hypertension can be controlled by the reduction of ACE activity and inhibition of bradykinin breakdown in blood vessels." (PMID 41234609, 2025). "Drugs like ACE inhibitors and ARBs for hypertension can interact with COVID-19 therapies." (PMID 39944605, 2025). "Interestingly, algal peptides have significant potential as natural inhibitors of ACE, making them promising candidates for managing hypertension." (PMID 40809316, 2025). "As such, it is a promising candidate for ACE inhibition and hypertension treatment." (PMID 40332402, 2025). "The CC and CT genotypes of the ACE gene were independently associated with hypertension, regardless of age, BMI, gender, and lifestyle factors." (PMID 40370871, 2025). "Therefore, effectively inhibiting ACE activity has emerged as a key therapeutic strategy for managing and treating hypertension." (PMID 40868867, 2025). "Taken together, these in silico findings support the hypothesis that IVGRPLANG and IGDEPRHQYL possess multitarget potential as antihypertensive agents capable of modulating a broad range of hypertension-related pathways beyond ACE inhibition." (PMID 40710492, 2025). "Previous research has identified risk factors for postoperative AKI, include male sex, age > 50 years, diabetes mellitus, hypertension, ascites, heart failure, emergency surgery, intraperitoneal surgery, polypharmacy, use of an “ACE” inhibitor or “ARB,” and increased ASA–PS scores." (PMID 40463683, 2025).
Hypertension (continued). "One of the main functions of ACE is the degradation of angiotensin I to produce the vasoconstrictor angiotensin II; due to this, ACE has become a therapeutic target for hypertension, congestive heart failure, myocardial infarction, renal disease, and diabetic nephropathy." (PMID 40305366, 2025). "ACE inhibitors also lower the risk of new-onset microalbuminuria or macroalbuminuria and reduce mortality in diabetic patients, regardless of hypertension." (PMID 39941397, 2025). "The exploratory growth phase (1983–1993) was marked by the use of nitroglycerin to treat angina, calcium channel blockers to treat hypertension, ACE inhibitors to treat heart conditions, the use of opioids in pain management therapy, and peptide and hormonal therapy." (PMID 40871092, 2025). "In the random forest model for predicting LV adverse or reverse remodeling, changes in LVEF and WMSI were among the top-ranked factors, along with symptom-to-balloon time, age, hypertension, diabetes mellitus, pharmacological treatments (beta-blockers and ACE inhibitors), and imaging-guided PCI." (PMID 40438233, 2025). "ACE inhibitors, e.g., used to treat hypertension, increase bradykinin levels." (PMID 40943067, 2025). "ACE inhibitors control hypertension by reducing angiotensin II formation, leading to vasodilation." (PMID 41008215, 2025). "Management of hypertension in CAH should prioritize angiotensin-converting enzyme (ACE) inhibitors and angiotensin-receptor blockers (ARBs) due to their cardioprotective properties, beneficial effects on endothelial function, and ability to improve insulin sensitivity." (PMID 40529825, 2025). "Similarly, ACE inhibitors and angiotensin receptor blockers (ARBs), commonly prescribed for hypertension and nephroprotection in diabetic patients, attenuate inflammatory responses by decreasing cytokine production and enhancing anti-inflammatory pathways." (PMID 41030257, 2025). "Although the specific mechanisms of hypertension remain unclear, the crucial role of angiotensin-I-converting enzyme (ACE) in controlling blood pressure has been clinically confirmed." (PMID 40077777, 2025). "Prolonged use of antihypertensive medications, such as ACE inhibitors or angiotensin receptor blockers (ARBs), in individuals with hypertension reduces the kidneys' ability to tolerate the toxic effects of some pharmaceuticals, thereby increasing the likelihood of postoperative AKI." (PMID 40100411, 2025). "Those with higher HE4 were more likely to have AAA, were significantly older, had higher levels of hypertension, congestive heart failure, and coronary artery disease, and were more likely to be taking angiotensin-converting enzyme inhibitors/angiotensin receptor blockers (ACE/ARBi)." (PMID 40722638, 2025). "Moreover, comparative trials assessing different antihypertensive drug classes across BMI strata, including ACE inhibitors or diuretics, would provide more comprehensive guidance for individualized hypertension management in diverse populations." (PMID 40352037, 2025). "We used a spontaneous hypertensive rat (SHR) model to systematically investigate for the first time that four food-derived ACE inhibitory peptides obtained from green tea dregs not only alleviate hypertension symptoms but also ameliorate renal fibrosis and inflammatory responses." (PMID 40284165, 2025). "Moreover, in terms of the development of hypertension control drugs, the substitution of food-derived ACE inhibitory peptides for chemical synthesis inhibitors has become a development trend in this field." (PMID 40807557, 2025). "Furthermore, treating hypertension with ACE inhibitors or angiotensin receptor blockers (ARBs) can increase ACE2 levels, making COVID-19 patients more vulnerable to SARS-CoV-2 infection and decreasing their prognosis." (PMID 40026986, 2025). "The continued use of ACE inhibitors or ARBs may be beneficial, especially in patients with ongoing functional impairments or hypertension." (PMID 41517446, 2025).
Hypertension (continued). "Furthermore, within the renin–angiotensin–aldosterone system, angiotensin II, generated by ACE from angiotensin I, acts as a potent vasoconstrictor, promoting hypertension." (PMID 39803290, 2025). "Consequently, synthetic ACE inhibitors such as captopril, lisinopril, and enalapril are widely employed in clinical settings to manage hypertension." (PMID 40649326, 2025). "A single genetic polymorphism of a gene such as ACE or AGTR1 may contribute to the risk of cardiovascular disease (CVD) and hypertension, either alone or in conjunction with other genetic factors." (PMID 40149592, 2025). "The I/D polymorphism in the ACE gene may be associated with susceptibility to DPN and hypertension in diabetic patients, highlighting the importance of considering genetic factors in the assessment." (PMID 41002725, 2025). "Given the complex relationship between ACE polymorphisms and brain structure, this study examines the influence of the ACE I/D polymorphism on brain volume in AD patients with and without hypertension." (PMID 40372199, 2025). "Antihypertensive drugs, especially ACE inhibitors, are essential in hypertension management." (PMID 40868867, 2025). "Research indicates that HHcy is independently linked to isolated systolic hypertension and may reduce the effectiveness of angiotensin-converting enzyme (ACE) inhibitors in patients with hypertension." (PMID 40943112, 2025). "On multivariable analysis, factors associated with increased odds of progression included Malay ethnicity, worsening albuminuria stage, presence of chronic diseases such as diabetes and hypertension, higher baseline systolic BP, smoking status, and baseline use of ACE inhibitor/ARB at maximal doses." (PMID 40904355, 2025). "Similarly, renin-angiotensin system blockers (ACE inhibitors or ARBs), as first-choice treatments for diabetes with hypertension, have been shown to significantly improve prognosis." (PMID 41255513, 2025). "It typically presents 3 months to 2 years post-transplant with symptoms such as worsening hypertension, hypokalemia, and kidney function decline when treated with angiotensin-converting enzyme inhibitors (ACE inhibitors) or angiotensin receptor blockers (ARBs)." (PMID 40142909, 2025). "Efforts in early detection continue: microalbuminuria screening in diabetes allows earlier ACE inhibitor use, and emerging biomarkers in hypertension may soon identify subclinical kidney damage for timely intervention." (PMID 41141162, 2025). "Also, in terms of cardiovascular health, for blood pressure regulation, GABA acts as an ACE (angiotensin-converting enzyme) inhibitor, reducing hypertension in hypertensive patients." (PMID 40806501, 2025). "As hypertension can also be managed by alterations in diet, as well as exercise regimes, there is an interest in identifying compounds present in foods that can modify metabolic enzymes such as ACE." (PMID 40007962, 2025). "Angiotensin-converting enzyme (ACE) inhibitors, commonly prescribed for hypertension and heart failure, may exert chondroprotective effects by modulating Ang II activity." (PMID 40688840, 2025). "More than half of our population had a hypertension history, with many taking medications such as ACE inhibitors, beta blockers, and angiotensin receptor antagonists, all of which may blunt natriuretic peptide release." (PMID 41477188, 2025). "An important factor in hypertension is angiotensin-converting enzyme (ACE)." (PMID 40807539, 2025). "Similarly, J. regia protein hydrolysate reduced blood pressure by inhibiting ACE activity in spontaneous hypertension rats' aorta and lung tissues, lowering TNF‐α levels, and increasing bradykinin and NO levels in the serum." (PMID 39803290, 2025). "Currently available ACE inhibitors, such as captopril, lisinopril, enalapril and trandolapril, do not offer efficient selectivity of cACE to limit these side effects during the treatment of hypertension." (PMID 39763019, 2025).
Hypertension (continued). "In addition to GABA and ACE-inhibitory peptides, chlorogenic acid, p-coumaric acid, and hesperetin had beneficial effects on hypertension, preventing atherosclerosis, with a proactive effect in lipid metabolism." (PMID 41295317, 2025). "Findings of this study indicated a potential association between the DD genotype of the ACE gene and elevated blood pressure, defined as SBP >140 mmHg or diastolic blood pressure >90 mmHg, with a prevalence of 38.2% in individuals with hypertension, compared to 33.4% in normotensive individuals." (PMID 41272596, 2025). "Another study used a radiation-induced hypertension model and found that taxifolin effectively suppressed hypertension by inhibiting angiotensin-converting enzyme (ACE) activity and preventing excessive production of angiotensin II, which causes vasoconstriction." (PMID 40869372, 2025). "Therefore, peptides that inhibit ACE are gaining attention for their potential in managing hypertension." (PMID 40809316, 2025). "Consequently, ACE inhibitors play a significant role in hypertension treatment by reducing angiotensin II production and elevating bradykinin levels." (PMID 40077539, 2025). "Beta-blockers and ACE inhibitors should be preferred for hypertension." (PMID 41230475, 2025). "Although MMP9 inhibition (by aldosterone antagonists and ACE inhibitors) represents a therapeutic approach for heart failure, atherosclerosis, hypertension, and myocardial infarction, patients with congestive heart failure demonstrate reduced Mmp9 mRNA levels in cardiac biopsies." (PMID 40869420, 2025). "However, their integration into hypertension management requires further research to assess their comparative efficacy with ARBs and ACE inhibitors." (PMID 40255834, 2025). "Similarly, quantum mechanical studies of angiotensin-converting enzyme (ACE) inhibitors have provided insights into their mechanism of action and guided the development of improved compounds for treating hypertension and heart failure." (PMID 40429800, 2025). "Consequently, angiotensin-converting enzyme (ACE) inhibitors have been successfully used in managing hypertension, anxiety, glaucoma, and cardiac events." (PMID 40509202, 2025). "Recent clinical data further support this effect: perindopril therapy in essential hypertensive patients was shown to reduce adrenaline-induced platelet aggregation over one month of treatment, suggesting ACE inhibitors can enhance NO-mediated anti-aggregatory function in vivo." (PMID 41154649, 2025). "Interestingly, different types of high blood pressure treatments (ACE inhibitors, beta blockers, and one ARB) showed similar types of protective effects." (PMID 40672496, 2025). "Currently, ACE inhibition is regarded as one of the most effective treatments for hypertension." (PMID 38540877, 2024). "The HOPE study investigated the impact of ramipril, an ACE inhibitor, in those who are at high risk of cardiovascular events with or without hypertension." (PMID 38716006, 2024). "Overall, the insights highlighted in this review could enable the rational design of novel ACE inhibitors with improved efficacy and safety profiles, ultimately leading to better therapeutic outcomes for patients with hypertension and cardiovascular diseases." (PMID 39046229, 2024). "What’s more, Nirendipine can be combined with ACE to treat diseases such as hypertension." (PMID 39450258, 2024). "Also, given the prevalence of ACE inhibitors for the treatment of hypertension, recommendations on the management of ACE inhibitor-induced angioedema in patients with SARS-CoV-2 infection would be beneficial." (PMID 38910667, 2024). "This is further illustrated by the co-administration of an angiotensin-converting enzyme (ACE) inhibitor in hypertension drug therapy to mitigate the peripheral oedema that accompanies calcium channel antagonists due to the venodilation imposed by ACE inhibitors." (PMID 38399239, 2024).
Hypertension (continued). "This indicates that AEPS has great potential as a natural ACE inhibitor for treating hypertension." (PMID 38474055, 2024). "Regarding antihypertensive potential, the extracts showed inhibitory activities on ACE, an enzyme that plays a key role in regulating vascular tone and blood pressure, suggesting that these extracts could help to prevent hypertension." (PMID 38254569, 2024). "Additionally, angiotensin-converting enzyme (ACE) inhibitors and angiotensin II receptor blockers (ARBs) are commonly used to manage hypertension and heart failure, providing benefits by dilating blood vessels and improving blood flow." (PMID 39131016, 2024). "Their ability to inhibit ACE, improve vascular tone, and protect cells from oxidative stress makes them interesting for use in medicine and the food industry as a preventive and therapeutic agent against hypertension." (PMID 39767622, 2024). "Moreover, peptides derived from peanut, quinoa, and flaxseed proteins are examples of compounds capable of inhibiting the angiotensin-converting enzyme (ACE), therefore, presenting anti-hypertension properties." (PMID 39635090, 2024). "Treatment strategies primarily revolve around the management of diabetes and hypertension, with medications, such as angiotensin-converting enzyme (ACE) inhibitors and angiotensin receptor blockers (ARBs), utilized to regulate blood sugar and blood pressure levels." (PMID 38646317, 2024). "The gene expression of ACE has been investigated as a possible hypertension marker." (PMID 38917192, 2024). "ACE inhibition is widely recognized as a critical strategy in managing hypertension." (PMID 39598284, 2024). "Therefore, simultaneous inhibition of renin and ACE is an effective therapy for controlling hypertension." (PMID 39796531, 2024). "In contrast, ACE inhibitors, a mainstay treatment for heart failure and hypertension, are not frequently associated with SJS." (PMID 38333456, 2024). "The in vivo results obtained in this study suggest that SBE may be effective, particularly in combination, in reducing ACE activity, highlighting its potential as a nutraceutical intervention for hypertension." (PMID 39728459, 2024). "Lisinopril is a widely‐prescribed ACE inhibitor (ACEi) for hypertension and heart failure." (PMID 38333911, 2024). "The results could enhance our understanding of the potential of P. minor as an ACE inhibitor, which may subsequently be developed as a preventive measure and complementary treatment for hypertension." (PMID 39598284, 2024). "In hypertension, ACE activity can be impaired by the condition itself or by therapy." (PMID 39684795, 2024). "The protein isolates of the seed also exhibited in vitro ACE inhibitory and hypocholesterolemic activities, suggesting the seed may contain bioactive nutrients that may be useful for managing hypertension and atherosclerosis." (PMID 38256745, 2024). "Hence, it is important to explore natural sources of ACE inhibitors with potentially fewer side effects for the prevention and complementary treatment of hypertension." (PMID 38474055, 2024). "The most commonly recommended antihypertensive medications for the first-line treatment of hypertension include (a) thiazide-type diuretics, (b) calcium channel blockers, (c) angiotensin-converting enzyme (ACE) inhibitors, and (d) angiotensin II receptor blockers (ARBs)." (PMID 39767622, 2024). "The protein isolates, however, further exhibited an in vitro inhibitory effect on α-glucosidase, α-amylase and ACE, which suggests that the seeds may be a source of bioactive proteins for postprandial glycemic control and management of hypertension." (PMID 38256745, 2024). "As a result, screening for cardiovascular disorders including hypertension, and creating novel ACE inhibitors from A. decursiva could be effective." (PMID 39309635, 2024).